HPSE (heparanase)
Diseases named in the same sentence as HPSE in open-access papers (continued):
Sharing a sentence is not in itself a finding about the gene and the disease.
tumor (continued). "Using in vitro assays of osteoclastogenesis and bone resorption, it was shown that enhanced osteoclastogenesis also requires the presence of syndecan-1, a proteoglycan whose shedding from tumor cell surfaces is enhanced by the expression of heparanase and protein agents, such as IL-8." (PMID 31847214, 2019). "Given the ability of heparanase to modulate pro-inflammatory cytokine levels, and activate and recruit tumor-promoting leukocytes, it is likely that heparanase plays a greater role in modulating the immune system and immune suppression during cancer progression." (PMID 31110966, 2019). "It is possible that in some tumor settings, heparanase inhibitors may inhibit leukocyte function, and consequently tip the balance away from tumor clearance and in favor of tumor progression." (PMID 31110966, 2019). "Taken together, the results obtained in the present study suggest that the heparanase enzyme (HPSE) released by tumor cells could diffuse within the microenvironment and impact neighboring tissues, such as circulating lymphocytes." (PMID 30922347, 2019). "Moreover, increased HPSE expression in circulating lymphocytes and tumor cells possibly stimulates exosome secretion, thereby promoting tumor progression." (PMID 30922347, 2019). "Recently, protein or messenger RNA (mRNA) expression of HPSE has been identified in various cancer cells and the over-expression of HPSE protein or mRNA in tumor cells has been reported and correlated with the metastatic potential of tumor cells in vitro and in vivo as well as with poor prognosis." (PMID 30333909, 2018). "Thus, examination of heparanase levels in the tumor metastases should be evaluated for most efficient precision medicine applying heparanase inhibitors." (PMID 29464068, 2018). "In certain tumour types EGR1 represses transcription of heparanase, which degrades heparan sulphate proteoglycan chains present in the ECM and basement membranes allowing tumour cells to spread and inducing the release of pro-angiogenic chemokines and growth factors." (PMID 30566430, 2018). "Importantly, the primary tumor biopsies exhibited a typical high heparanase enzymatic activity that was maintained in the corresponding PDX (patient 1709), or increased in the metastatic lesion originating from the PDX." (PMID 29721203, 2018). "Moreover, counterintuitively to the generally accepted notion of a pro-malignant action of heparanase, nuclear localization was correlated with differentiation in various tumor cellular models and with a favorable outcome in patients with head and neck cancer." (PMID 30413079, 2018). "Interestingly, tumors in which heparanase expression was different between the primary tumor and its metastases exhibited inferior prognosis compared with tumors in which heparanase expression was stable." (PMID 29464068, 2018). "Heparanase is an endoglucuronidase that cleaves heparan sulfate chains of proteoglycans, and high heparanase expression and activity have been correlated with an aggressive tumor phenotype in HCC." (PMID 30297672, 2018). "Soluble heparanase, in turn, could be taken up by both tumor cells and macrophages, enhancing the expression of pro-tumorigenic genes." (PMID 30413079, 2018). "This hypothesis is also supported by several in vivo studies where HPSE inhibitors reduced tumor growth." (PMID 30487472, 2018). "Interestingly, patients in which heparanase staining between primary tumor and metastasis was changed exhibited worse prognosis vs patients exhibiting stable heparanase pattern (HR 0.035; p = 0.005)." (PMID 29464068, 2018). "Since autophagy confers an advantage to tumor-cell, by escaping from cell death, targeting synergistically heparanase and autophagy may be an additional strategy in cancer treatment." (PMID 30487472, 2018).
tumor (continued). "The involvement of heparanase and HSPG in the production, composition, and docking of exosomes from tumor and stromal cells, eventually triggering an aggressive phenotype, expands the known impact of heparanase/HSPGs axes in tumor biology and further supports their roles as therapeutic targets." (PMID 30413079, 2018). "Notably, heparanase induction correlated with increased tumor metastasis, and with reduced patient survival." (PMID 29721203, 2018). "Therefore, CAR-T cells attacking solid tumors must be able to degrade HSPGs by releasing heparanase (HPSE) to access tumor cells." (PMID 29449531, 2018). "In addition to its important roles in physiology and development, heparanase mediates numerous pathological processes such as tumour growth, metastasis, angiogenesis and inflammation." (PMID 30441818, 2018). "In addition, PG545 resulted in decreased levels of Erk phosphorylation (second panels) and accumulation of macrophages in the tumor periphery, resembling localization of macrophages in tumors developed in heparanase-knockout mice." (PMID 29721203, 2018). "Indeed, reported findings suggest that heparanase and HSPGs synergize to foster tumor growth and progression." (PMID 30413079, 2018). "This may provide an experimental base for molecular imaging of tumor highly expressing heparanase using HPA mAbs." (PMID 29671088, 2018). "Interestingly, an overexpression of heparanase is well-documented in multiple pathological conditions such as inflammation, angiogenesis, angiogenesis, tumor metastasis, and atherosclerosis." (PMID 30555321, 2018). "Similarly to heparanase, the two extracellular endosulfatases, Sulf-1 and Sulf-2, were found to be dysregulated in a wide range of human malignancies where they affect the tumor microenvironment and cell signaling by modifying the structure and function of HS." (PMID 30413079, 2018). "Therefore, modification of the glycocalyx (HSPG in particular) in the tumor microenvironment by Sulf1, Sulf2, or heparanase affects cancer cell proliferation, signaling, invasion, and metastasis." (PMID 30135409, 2018). "Accumulating evidence indicates, however, that heparin derivatives and HS mimetics can affect tumor biological behavior by exerting pleiotropic effects through a context-specific mechanism of action based not only on heparanase inhibition, but also on the counteraction of HSPG functions." (PMID 30413079, 2018). "In addition to remodeling of ECM, human heparanase regulates multiple signaling cascades involved in tumor cell survival, angiogenesis and metastasis." (PMID 28359266, 2017). "Referring to HSPG-dependency that probably triggers tumor cell resistance, we proposed three potential pathways: i) Heparanase, the sole endoglycosidase in mammals modulates HSPGs and is considered as a bad prognostic marker in multiple malignant diseases, which also triggers resistance." (PMID 28978053, 2017). "It is well accepted that HPSE enzymatic activity contributes to glomerular basement membrane disassembly and proteinuria in several experimental and human glomerulopathies as well as to sustain angiogenesis and tumor cell migration in cancer progression." (PMID 29097791, 2017). "Furthermore, the activity of heparanase (HPSE), the only endoglucuronidase that specifically cleaves HS, is closely related to growth and metastasis in tumor cells." (PMID 28388549, 2017). "This relationship between HPSE expression and tumor cell metastasis was first reported in 1983." (PMID 28388549, 2017). "Subgroup analysis using the predetermined cut-off value revealed that high HPSE expression was associated with larger tumor sizes without significant heterogeneity (OR = 3.35, 95% CI = 2.39 – 4.68, P < 0.00001, I2 = 45%)." (PMID 28388549, 2017).
tumor (continued). "Obviously, triggered by the glycosaminoglycan (GAG) structure of heparin, LMWHs can interfere at various stages of the metastatic cascade and thus attenuates tumor cell adhesion, growth factor activity, angiogenesis, enzymatic heparanase activity and thrombin-induced prometastatic signaling." (PMID 28978053, 2017). "Heparanase expressed in cancer cells and cells of the tumor microenvironment provides a most appropriate therapeutic molecular target and could serve a decisive role in cancer regime." (PMID 28359266, 2017). "Interestingly, similar to their roles in regulating tumour angiogenesis and metastasis, heparanase and syndecans also work together in regulating exosome secretion by tumour cells." (PMID 27408707, 2016). "Related to its endoglycosidase activity, heparanase may function as a potent modulator of tumor behavior due to its pro-tumorigenic, pro-angiogenic and pro-metastatic activities." (PMID 27322195, 2016). "Growing preclinical and clinical evidence suggests that the heparanase/heparan sulfate (HS) system, a crucial regulator of biological processes in the tumor and its microenvironment, might represent a valuable therapeutic target." (PMID 27374103, 2016). "Heparanase is a well-known pro-metastatic molecule with a high activity in most tumor cells." (PMID 26689987, 2016). "In addition, heparanase seems to regulate secretion, composition, and function of tumor cell-derived exosomes." (PMID 27322195, 2016). "Moreover, several investigators reported that heparanase activity was high in tumor cells and involved in cancer metastasis and angiogenesis." (PMID 26849680, 2016). "Tumor cells need to degrade basement membrane constituents in order to promote metastasis, and this activity of malignant cells involves proteinases and other enzymes such as heparanase." (PMID 25351637, 2015). "Heparanase-1 degrades heparan sulfate and has been correlated with tumor progression." (PMID 25351637, 2015). "A heparanase-1 degrada heparam sulfato e está relacionada à progressão de tumor." (PMID 25351637, 2015). "HPSE overexpression correlates with the invasive potential of the tumor in vitro." (PMID 26488476, 2015). "Increased HPSE expression was found in numerous tumor types and correlates with poor prognosis, and downregulation of heparanase expression results in suppression of tumor invasion and migration, especially in HCC cells." (PMID 26839882, 2015). "It is well known that heparanase-1 shows a direct correlation with tumor metastasis." (PMID 25351637, 2015). "HPSE is believed to play an important role in the process of tumor invasion and metastasis." (PMID 26839882, 2015). "This section highlights some of the prevalent cancer types, which have reported significant alterations in heparanase, Sulf1, and/or Sulf2 and how these changes in expression correlate with indices of cancer progression such as prognostic indicators, tumor development, metastasis, and survival." (PMID 25105093, 2014). "In contrast, the methylation of heparanase had no apparent associations with the following prognostic factors: tumor size (p = 0.078), node metastasis (p = 0.133), ER positivity (p = 0.101), PgR positivity (p = 0.528), and HER2 expression (p = 0.196)." (PMID 24632672, 2014). "Moreover, in all heparanase-positive tumours the pattern of p16 protein staining was similar to that of heparanase expression in defined areas of the tumour." (PMID 24286246, 2014). "Available information suggests that heparanase may function as a regulatory factor in different pathological conditions, including tumor and inflammation, exerting its functions through modification of HS structure." (PMID 25157361, 2014).
tumor (continued). "Heparanase released from activated platelets and cells of the immune system facilitates extravasation of inflammatory and tumor cells and also stimulates endothelial mitogenesis, primarily through release of HS-bound growth factors (i.e., FGF, HGF, VEGF) residing in the ECM." (PMID 24465803, 2014). "A large number of these studies found a direct connection between the enzyme level in the tumor and the aggressiveness of the disease, implying that the heparanase level could function as a prognostic predictor." (PMID 24887057, 2014). "Cancer patients exhibiting high levels of heparanase had a significantly shorter postoperative survival time than patients whose tumors contained low levels of heparanase due, in part, to increased tumor metastasis and tumor angiogenesis." (PMID 24465803, 2014). "Among twelve p16-positive tumours examined, 10 (83.3%) were also positive for heparanase." (PMID 24286246, 2014). "As it is reported that heparanase expression is correlated with tumor size and clinical progression stage, it is interesting to speculate that heparanase may be participating in tumor growth in vivo." (PMID 24632672, 2014). "Furthermore, heparin was shown to inhibit heparanase activity, an essential activity for tumor neovascularization and growth." (PMID 24073244, 2013). "Importantly, PG545 treatment reduced heparanase expression in the primary tumor and at metastatic foci." (PMID 23984412, 2013). "Heparanase was found to regulate secretion and function of tumour cell-derived exosomes." (PMID 26082318, 2013). "Heparanase was detected in the lung tissue from non-inoculated age-matched control mice, but comparing these levels with those in the tumor-bearing vehicle-treated mice indicates that heparanase was elevated more than double the basal level in the tumor-bearing mice." (PMID 23300607, 2012). "The high expression of heparanase in the tumor tissue was confirmed using an ELISA method." (PMID 23300607, 2012). "While a decisive role of heparanase in cellular invasion and tumor metastasis is well documented, the function that heparanase plays in primary tumor progression is largely unknown, but likely involves angiogenic and signaling aspects." (PMID 23251556, 2012). "In addition to blocking a common angiogenic signalling pathway in tumor cells, the expression of heparanase in the primary tumor and lung was also significantly reduced by PG545 treatment." (PMID 23300607, 2012). "Additionally, heparanase released from activated platelets and tumor cells induce up-regulation of TF in the cells." (PMID 23908827, 2012). "Upon secretion of heparanase from metastatic tumour cells, the enzyme hydrolyses the glycosidic bonds of heparan sulphate chains attached to proteoglycans to products 10–20 sugar units in length, leading to penetration of the endothelial cells of blood vessels and target organs by the tumour cell." (PMID 22719856, 2012). "While heparanase function in tumor biology is well documented and heparanase inhibitory compounds are being developed as anti-cancer drugs, emerging evidence indicate that heparanase is also engaged in several other pathological disorders." (PMID 21364956, 2011). "Notably, while heparanase inhibitors attenuated tumor progression and metastasis in several experimental systems, other studies revealed that heparanase also functions in an enzymatic activity-independent manner." (PMID 23908791, 2011). "In addition, the role of heparanase in tumor angiogenesis, the prognostic significance of heparanase over-expression for ccRCC are described." (PMID 22133010, 2011). "However, if heparanase is clearly associated to protumorigenic effects, contradictory observations have been made concerning SULF1 and SULF2 contribution in human neoplasia, as we have discussed in this article." (PMID 21599997, 2011).
tumor (continued). "The finding that syndecan-1 shed from the surface of tumor cells is another important mediator of osteoclastogenesis identifies the heparanase–syndecan-1–cytokine axis as a novel target for inhibiting osteoclastogenesis and ultimately for preventing the consequences of bone metastases." (PMID 20200931, 2010). "In this paper, we hypothesize that CXCL7 increases the expression of VEGF-C, VEGF-D, and heparanase, and increases cell invasion via CXCR2 signaling, all linked to tumor lymphangiogenesis and metastasis." (PMID 20652010, 2010). "Thus the enhanced bone resorption observed with the heparanase-expressing tumor cells is due to their impact on osteoclastogenesis (ie, increased osteoclast numbers) and not an effect of any increase in the activity or size of the individual osteoclasts." (PMID 20200931, 2010). "Alterations in the expression pattern of HS at the surface of tumor cells, due to reduced biosynthesis of HS and/or increased expression of heparanase, can explain, at least partly, the fact that many cancer cells show increased susceptibility toward certain CAPs." (PMID 19527490, 2009). "Moreover, heparanase upregulation correlates with increased tumor vascularity and poor post-operative survival of cancer patients." (PMID 19360105, 2009). "We and others have speculated that heparanase acts as a master regulator of the aggressive tumor phenotype." (PMID 19305494, 2009). "Heparanase mRNA expression has been investigated in a wide variety of human tumours." (PMID 17437011, 2007). "Heparanase is expressed by a variety of cell types and helps the cells to cross physiological boundaries, as is the case with trophoblasts in the placenta, leukocyte extravasation, or tumour cell metastasis." (PMID 11953884, 2002). "Heparanase expression has been studied in human primary tumours and tumour cell lines." (PMID 11953884, 2002). "We could confirm previous results that heparanase expression levels are higher at the primary tumour site than at metastatic sites." (PMID 11953884, 2002). "In our study, heparanase was expressed in the majority of tumour specimens and expression at the invading edge of tumours could be demonstrated." (PMID 11953884, 2002). "Prognostic factors include clinical features like tumor size (especially > 1 cm for nodular lesions), ulceration, and neck lymphadenopathy, as well as histological features like Ki67 expression, BAP1 loss, heparanase expression, and potentially depth of invasion." (PMID 40344340, 2025). "For example, when compared with bone marrow-restricted MM, EMD is often characterized by a reduction in adhesion molecules and an increase in extracellular matrix degrading enzymes, such as heparanase, which may contribute to tumor spread and lower ORR in these patients." (PMID 41335212, 2025). "Likewise, many clinical association studies have consistently demonstrated that upregulation of heparanase expression correlates with increased tumor size, tumor angiogenesis, enhanced metastasis, and poor prognosis, providing strong support for the pro-tumorigenic function of the enzyme." (PMID 38334603, 2024). "Thus, our findings contribute to further knowledge of autophagy regulation by HPSE, supporting the view that the use of clinically applicable autophagy inhibitors may be one of the important strategies for the control of tumor growth progression." (PMID 37508554, 2023). "Several other mechanisms that tie heparanase-1 with cancer progression have been described, as is the case for the involvement of heparanase-1 in immune response modulation, enhanced exosome formation in tumor cells, as well as in autophagy leading to chemotherapy resistance." (PMID 36680276, 2023). "Notably, targeting heparanase to the mammary epithelium promotes tumour growth and metastasis." (PMID 34982945, 2022).